SPOP (speckle type BTB/POZ protein)
Diseases named in the same sentence as SPOP in open-access papers (continued):
Sharing a sentence is not in itself a finding about the gene and the disease.
cancer (continued). "SPOP specifically regulates Caprin1-dependent SG assembly in C4-2 cells, and PCa-associated SPOP mutations enhance cancer cell survival by elevating Caprin1 levels." (PMID 40521202, 2025). "Mutations in SPOP that occur in cancer disrupt this regulatory mechanism, leading to the accumulation of NANOG and the promotion of cancer stem cell properties, ultimately contributing to prostate cancer progression." (PMID 40227962, 2025). "LLPS concerning gene fusions and mutations can also affect cancer through many pathways, such as SPOP–DAXX bodies, PML vesicles and FET fusion proteins." (PMID 39006762, 2024). "Normally, SPOP assembles with substrates and recruits to the nucleosome, but cancer‐associated mutations disrupt the SPOP/substrate colocalization mechanism and substrate‐mediated LLPS of ubiquitin ligases." (PMID 39006762, 2024). "As part of our study, we assessed that SPOP was anomalously expressed in kinds of cancers, associated with clinical stage and outcomes." (PMID 39074086, 2024). "The ability of SPOP, a cancer-associated substrate adaptor in the ubiquitination machinery, to self-associate is important for its role in biology and disease." (PMID 36856266, 2023). "SPOP is thus an important regulator of cellular signalling, and mutations in SPOP are associated with a variety of cancers." (PMID 36856266, 2023). "Take the tumor suppressor speckle-type BTB/POZ protein (SPOP) for example, SPOP can form liquid-like droplets via interaction with its substrates, which can inhibit cancer-associated protein aggregation." (PMID 37968256, 2023). "Herein, cancer mutations in the tumor suppressor speckle-type BTB/POZ protein (SPOP) were found to be associated with specific phase separation defects." (PMID 37127623, 2023). "Cancer mutations disrupt SPOP-substrate interaction, thereby disrupting SPOP phase separation and localization of membrane-free organelles." (PMID 37127623, 2023). "Using SAXS experiments of a cancer variant of SPOP we also show how our approach can be used to determine changes in the level of self-association." (PMID 36856266, 2023). "They found that cancer-associated SPOP mutations result in diminished IRF1 degradation, and consequentially increased expression of the IRF1-driven immune-suppressive PD-L1." (PMID 37622993, 2023). "These cancer-associated mutations are frequently located in the MATH domain of SPOP, which is responsible for substrate binding." (PMID 37705755, 2023). "It is worth noting that the SPOP gene often undergoes mutations in cancers, especially within the MATH domain, leading to the destruction or decrease of substrate affinity." (PMID 37796126, 2023). "IDC-P is common in the TCGA molecular subset of SPOP mutant cancers, and the presence of SPOP mutations are more likely in IDC-P bearing tumors." (PMID 38067216, 2023). "Most studies have reported that Aur-A is involved in the growth regulation of various cancers and associated with drug resistance, and SPOP E3 ubiquitin ligase was identified as a substrate of Aur-A." (PMID 35831273, 2022). "Accumulating evidence from cancer cell lines and animal models has demonstrated that SPOP mutations promote the initiation and progression of EC and PCa, potentially owing to the dysregulation of SPOP-mediated ubiquitination of its substrates." (PMID 36585710, 2022). "Nowadays, mutations or variations of SPOP are one of the potential causes of the dysfunction of the proteasome pathway in diverse cancers." (PMID 35847355, 2022). "Research has shown that cancer-associated SPOP mutants generally display an impaired capacity to bind substrates, leading to reduced ubiquitination of substrates." (PMID 36585710, 2022). "Recently, SPOP has attracted major research attention as it is frequently mutated in a range of cancers, highlighting pleiotropic tumorigenic effects and associations with treatment resistance." (PMID 36360288, 2022).
cancer (continued). "More importantly, cancer-associated mutations clustered in the MATH domain of SPOP impaired the interaction between SPOP and PrLZ, thereby leading to the accumulation of PrLZ protein in PCa." (PMID 35194188, 2022). "The cancer-related SPOP mutation interferes with the recruitment of ligase substrates, leading to the accumulation of proto-oncoproteins, triggering phase separation of SPOP and colocalization of membrane-free organelles in cells." (PMID 36081552, 2022). "SPOP variants have been reported in many types of cancer, including prostate (PrCa), endometrial cancer (EC), ovarian, liver, thyroid, breast and kidney cancers amongst others." (PMID 36360288, 2022). "Taken together, our data indicate that cancer-derived BRAF mutations occurring in the SBC motif allow BRAF to evade SPOP-mediated ubiquitination." (PMID 36585710, 2022). "Recurrent SPOP mutations have also been detected in other cancer types, although at a relatively low frequency." (PMID 36585710, 2022). "Will cancer-associated mutation of PrLZ impair its interaction with SPOP and evade SPOP-mediated degradation?" (PMID 35194188, 2022). "Cullin3-ring ubiquitin ligase is associated with a variety of solid tumors, and SPOP as its substrate adapter is one of the first cancer-specific related proteins to undergo phase isolation." (PMID 36497453, 2022). "This meta-analysis revealed that up-regulation expression of SPOP was associated with early cancer stage, well differentiation and better overall survival." (PMID 34838022, 2021). "Owing to the SPOP role in the regulation of the proteins involved in cell protection, a mutation in the MATH domain blocks the binding of SPOP to the substrate, hence it causes cancer development." (PMID 33906413, 2021). "Among patients with SPOP mutations, 56.3% showed metastasis at the time of diagnosis of primary cancer, compared with only 11.5% of the patients with wild-type SPOP (OR, 6.58, 95% CI, 5.81-7.46, P = 0.000)." (PMID 34322378, 2021). "We show that cancer-associated SPOP mutations impair Geminin K27-linked poly-ubiquitination and induce replication origin over-firing and re-replication." (PMID 34599168, 2021). "Pooled results indicated that up-regulation expression of SPOP was associated with early cancer stage, well differentiation and better overall survival." (PMID 34838022, 2021). "DNA methylation inhibitor 5-azacytidine effectively reverses expression of the TSGs examined, inhibits SPOP-mutated PCa cell growth in vitro and in mice, and enhances docetaxel anti-cancer efficacy." (PMID 34588438, 2021). "SPOP is implicated in oncogenesis since it is frequently mutated in human cancers such as prostate and endometrial cancers." (PMID 34599168, 2021). "Cancer-associated SPOP mutants show reduced binding, ubiquitination and degradation of oncoprotein substrates such as the androgen receptor and the ETS transcription factor ERG." (PMID 32365080, 2020). "In the present study, we aimed to define the role of cancer-specific SPOP mutations as radiosensitizing factors in preclinical models of PCa." (PMID 32512734, 2020). "Most of these residues are part of SPOP substrate-binding cleft, and all mutations were classed as putative drivers of cancer." (PMID 33333852, 2020). "The function of SPOP mutation in other cancer-related pathways is still unclear, and further studies are needed to investigate its mechanism." (PMID 33336059, 2020). "Cancer mutations in SPOP negatively regulate the LLPS process between SPOP and substrates and prevent their ubiquitination, leading to upregulation of these proteins and impaired proteostasis." (PMID 30967892, 2019). "Somatic SPOP missense mutations are frequently detected in several cancer types including endometrial and prostate cancer." (PMID 31350900, 2019). "Collectively, these results show that SPOP inhibits Hh pathway through destabilizing the transcriptional factor GLI2/3, which is abolished in cancers due to SPOP mutations." (PMID 30407707, 2019).
cancer (continued). "Nevertheless, these data suggest that Q165P PDX represents a useful in vivo model for investigation of cancer biology and drug targeting of SPOP mutations in human PCa." (PMID 31559706, 2019). "Because SPOP mutations can be detected in HGPINs adjacent to cancers, SPOP mutations are likely to be early events in prostatic carcinogenesis." (PMID 29581876, 2018). "In OCCC, the mutation rate of SPOP is 11.1% (1/9) according to COSMIC (Catalogue Of Somatic Mutations In Cancer) database." (PMID 29986747, 2018). "The experiments show that the cancer cells with high levels of genomic instability also often had mutations in a gene that encodes a protein called SPOP." (PMID 26374986, 2015). "When both of these pathways were inactivated—one by the SPOP mutation, the other by the drug—the cancer cells died more quickly." (PMID 26374986, 2015). "Together, these findings expand our understanding of SPOP mutation‐associated functional diversity and suggest that certain cancer‐associated variants might be repurposed as TPD‐competent E3 ligases for therapeutic applications." (PMID 41532714, 2026). "This classification may help in understanding the heterogeneity of SPOP-mutated cancers and tailoring treatment strategies accordingly." (PMID 40432836, 2025). "Importantly, for cancers with SPOP loss-of-function mutations, SPOP ligand-based PROTACs are ineffective." (PMID 40521202, 2025). "However, cancer-derived SPOP mutations disrupt the SPOP-53BP1 interaction, leading to HR defects and chromosomal instability." (PMID 40521202, 2025). "Dysregulation of SPOP-mediated ubiquitination has been implicated in several cancers." (PMID 40521202, 2025). "Notably, PCa-associated mutations in SPOP or the S68Y mutation in Nanog disrupt SPOP-mediated degradation of Nanog, leading to elevated cancer stem cell traits and PCa progression 63,64." (PMID 40521202, 2025). "Cancer patients with PDK1 mutations exhibit oncogenic effects by evading SPOP recognition." (PMID 39048965, 2024). "Moreover, recent studies have indicated SPOP to be a frequently mutated hotspot in several cancer types such as primary prostate, kidney, and endometrial cancer." (PMID 39680603, 2024). "Moreover, we classified the high-risk subgroup as a pro-cancer group with lower mutation rates of key genes (SPOP and MUC16), multiple low expression of immune-associated molecules, and differential expression of macrophages (M1 and M2)." (PMID 38643190, 2024). "However, this binding activity can be abolished by SPOP mutations in PCa, resulting in AR stabilization and the promotion of cancer cell proliferation and metastasis." (PMID 37847340, 2024). "Since, several studies indicated that a higher CD4+, CD8+ T cell infiltration scores were associated with better survival in cancers, it is reasonable that high expression of SPOP may recruit more TICs and result in a better survival." (PMID 39074086, 2024). "Subsequently, prognostic subgroups based on key genes classified the high-risk group as a pro-cancer subgroup that had lower mutation rates of critical genes (SPOP and MUC16), multiple low-expression immune-relevant molecules, and differences in macrophages (M1 and M2) expressions." (PMID 38643190, 2024). "Once mutated, SPOP impairs substrate binding and polyubiquitination, thereby affecting various cancer-related pathways including AR signaling, DNA repair and methylation, cancer metabolism, and immunity." (PMID 39748950, 2024). "SPOP has been a frequently mutated hotspot, especially in many cancer types." (PMID 39680603, 2024). "Finally, either downregulation of SPOP or gene mutations will promote the stabilization of downstream proteins of SPOP that will subsequently promote the progression of cancers." (PMID 35847355, 2022).
cancer (continued). "Next, we investigated the effect of cancer-associated SPOP mutations on BRAF localization." (PMID 36585710, 2022). "Moreover, PC3 separated cancers harboring truncal mutations in SPOP and FOXA1 from the ones harboring gene fusions involving ETS family transcription factors 25–28." (PMID 34857732, 2021). "The accumulation of oncogenic SPOP substrate proteins causes cancer." (PMID 34334791, 2021). "Biologically, knockdown PDK1 could significantly decrease mutated SPOP-induced cancer cell malignant phenotypes." (PMID 34353330, 2021). "Cancer-associated SPOP mutations impair DNA replication surveillance and cause replication origin over-firing and re-replication, thereby increasing replication stress and sensitizing cancer cells to ATR inhibition." (PMID 34599168, 2021). "Recent studies have indicated that somatic mutations in the SPOP gene are cancer-driven and might affect the therapeutic response." (PMID 34322378, 2021). "Indeed, the E3 ligase most frequently involved in degron loss is the known tumor suppressor gene SPOP, which suggests a selective pressure to avoid protein degradation in a variety of cancer types." (PMID 34795215, 2021). "SPOP is frequently mutated in certain human cancer types and implicated in tumorigenesis." (PMID 34599168, 2021). "Although the molecular characteristics of SPOP as well as a variety of ubiquitinated substrates of the SPOP/CUL3 E3 complex have been well elucidated, the pathophysiological cellular functions of both wild-type SPOP and cancer-associated SPOP mutants are still unclear." (PMID 33023230, 2020). "Although the molecular properties of SPOP and its cancer-associated mutants have been intensively elucidated, their cellular functions remain unclear." (PMID 33023230, 2020). "Thus, co-crystallization analysis of various cancer-associated SPOP mutants and substrates revealed the structural mechanisms by which these SPOP mutants change their affinity to substrates." (PMID 33023230, 2020). "A previous genome-wide linkage study revealed a series of single nucleotide polymorphisms (SNPs) in SPOP located on 17q12–21.32, and these SNPs may play an important role in gliomagenesis and cancer progression." (PMID 31901237, 2020). "Somatic point mutations in SPOP were found in six cancer samples from five foci in five patients." (PMID 31537872, 2019). "Significantly, cancer-derived SPOP mutations impair SPOP-DAXX colocalization." (PMID 31350900, 2019). "Moreover, SPOP mutations enhance cancer cell survival and resistance to docetaxel, a synthetic analog of paclitaxel by upregulating Caprin1-dependent SGs." (PMID 31771591, 2019). "To explore whether the cancer‐derived mutations affect SPOP interaction with GLI2/3, we carried out co‐IP assays and found that only wild‐type SPOP interacted with GLI2/3." (PMID 30407707, 2019). "However, we observed two cancer samples with both SPOP or FOXA1 mutations and fusion of an ETS transcription factor." (PMID 31537872, 2019). "We examined the interactions between cancer-associated mutants of SPOP and Caprin1 by co-IP assays." (PMID 31771591, 2019). "This understanding may help with the development of potential therapeutic approaches for patients bearing SPOP mutations and cancer metastasis." (PMID 29996942, 2018). "Interestingly, some of the recently uncovered potential cancer genes with hotspot mutations, e.g., SPOP and U2AF1, appear to exhibit fewer traits characteristic of the typical oncogenes such as promoting cancer cell growth or conferring oncogene dependence." (PMID 28740126, 2017). "Importantly, cancer-derived SPOP mutations disrupt their binding with HDAC6 and are thereby deficient in promoting HDAC6 destruction." (PMID 28599312, 2017). "Additionally, SPOP mutated patients also obtained some other genetic alterations, which could be the main reason why only got few differences between SPOP-mutated and SPOP-WT cancer tissues." (PMID 29262542, 2017).
cancer (continued). "Quantitative proteomics reveal distinct activities of speckle‐type POZ protein (SPOP) cancer mutants." (PMID 41532714, 2026). "Speckle‐type POZ protein (SPOP) functions as the substrate adaptor of the Cullin3‐RING ligase complex and is recurrently mutated in multiple cancer types." (PMID 41532714, 2026). "In this study, we explored the role of SPOP in cancer, focusing on its expression patterns, prognostic significance, and its relationship with immune cell infiltration in LUAD." (PMID 40657370, 2025). "We selected 786-O, HepG2, and MDA-MB-231, 3 cancer cell lines with high expression of SPOP and RIPK1, for further verification." (PMID 41122967, 2025). "A comprehensive understanding of the molecular mechanisms of SPOP in different cancer types will provide new insights into its function in oncogenesis, potentially advancing anti-cancer drug development." (PMID 40521202, 2025). "In conclusion, targeting the dysregulation of the SPOP-BRAF interaction presents a potential therapeutic strategy for cancers characterized by aberrant MAPK/ERK signaling." (PMID 40521202, 2025). "Our findings showed that SPOP-mutant cancer cells were at a higher risk of NE rupture and may be more susceptible to farnesyltransferase inhibition, providing a potential therapeutic avenue for targeting cancers with a high risk of NE rupture, such as those with SPOP mutations." (PMID 40662365, 2025). "We also showed that cancer-associated mutations in SPOP led to decreased levels of LMNB2 and compromised NE integrity, making SPOP-mutant cells more susceptible to NE rupture and vulnerable to farnesyltransferase inhibition." (PMID 40662365, 2025). "The E3 ligase SPOP plays a context-dependent role in cancer by targeting specific cellular proteins for degradation, thereby influencing cell behavior." (PMID 41148213, 2025). "Emerging insights into the diverse substrates of SPOP across various cancer types reveal a complex network of interactions that can either promote or inhibit tumorigenesis." (PMID 40521202, 2025). "For instance, the SPOP protein has participated in controlling several cancer-related substrates and is essential for mediating PD-L1 degradation." (PMID 40697329, 2025). "To comprehensively understand the role of SPOP in antitumor immunity and drug response, we conducted a stepwise analysis of the cancer-immunity cycle and drug sensitivity." (PMID 40657370, 2025). "Given that cancer is often characterized by an imbalance between apoptosis and necroptosis, we investigated the role of the SPOP/RIPK1/RIPK3 axis in tumors." (PMID 41122967, 2025). "Here, we summarize the latest findings on SPOP's functions and structural features, its regulatory mechanisms, the roles of its substrates in various cancers, and SPOP-targeting strategies." (PMID 40521202, 2025). "These small molecules have shown anti-cancer activities in vitro cellular models, but as with SPOP inhibitors, further research is needed to establish their anti-cancer activity in in vivo models." (PMID 39851497, 2025). "Understanding the SPOP gene and its protein product is essential for grasping its significance in various cellular processes and its involvement in diseases, especially cancer." (PMID 40432836, 2025). "SPOP functions as a pivotal regulatory hub, orchestrating a broad spectrum of cellular processes critical to tumorigenesis across various cancer types." (PMID 40521202, 2025). "Other recurrent cancer mutations highlight similar opportunities: BRAFV600E generates a degron-like patch that engages KEAP1, while mutations in the SPOP (speckle-type POZ protein) MATH (meprin and TRAF homology) domain rewire its substrate specificity." (PMID 41452132, 2025). "To gain deeper insights into the biological functions of SPOP in LUAD, we analyzed the correlation between SPOP expression and GSVA scores across 14 hallmark cancer-related pathways." (PMID 40657370, 2025).